KLF2 (KLF transcription factor 2)
Diseases named in the same sentence as KLF2 in open-access papers (continued):
Sharing a sentence is not in itself a finding about the gene and the disease.
leukemia (6 papers, 2022 to 2024). A malignant (clonal) hematologic disorder, involving hematopoietic stem cells and characterized by the presence of primitive or atypical myeloid or lymphoid cells in the bone marrow and the blood. "Accordingly, lentivirus-mediated knockdown of KLF2 antagonized leukemia cell suppression induced by lovastatin, associated with higher ERK1/2 phosphorylation compared to control." (PMID 37016335, 2023). "We found that the expression of KLF2 in B-ALL at diagnosis was positively correlated with the percentage of leukemia cells and the positive rate of MRD, indicating that KLF2 is a marker of poor prognosis." (PMID 39906661, 2024). "Strikingly, we found that in the KLF2-low group of B-ALL patients, the percentage of leukemia cells in the bone marrow was significantly lower than in the KLF2-high group at disease diagnosis (p = 0.04)." (PMID 39906661, 2024). "Inhibition of MAPK/ERK and higher cholesterol activity by KLF2 are likely mechanisms by which lovastatin suppressed leukemia progression in culture and in vivo." (PMID 37016335, 2023). "This new anti-proliferative property of the compound triggers upregulation of cell cycle inhibitor P21CIP1 and transcription factor KLF2, partly involved in leukemia suppression." (PMID 36335089, 2022). "This suggests that KLF2 may inhibit NK cell proliferation, promoting immune escape in leukemia and increasing the leukemic burden." (PMID 39906661, 2024). "Similarly, the leukemia blast-high group exhibited a modestly higher relative expression of KLF2 compared to the leukemia blast-low group, although the difference was not statistically significant (p = 0.21)." (PMID 39906661, 2024). "Furthermore, we found that the expression of KLF2 in B-ALL at diagnosis was positively correlated with the percentage of leukemia cells and the positive rate of minimal residual disease (MRD), indicating that KLF2 is a marker of poor prognosis." (PMID 39906661, 2024). "KLF2 regulates the expression of a subset of cholesterol biosynthesis genes, that may further contribute to leukemia suppressing activity of lovastatin." (PMID 37016335, 2023). "And KLF2 has also been shown to inhibit the proliferation and growth of Jurkat T leukemia cells." (PMID 37386390, 2023). "In conclusion, we show that lovastatin blocks leukemia proliferation in part through activation of cholesterol biosynthesis and induction of the transcription factor KLF2, capable of suppression the MAPKinase pathway, likely through downregulation of FAM83A and DDIT4." (PMID 37016335, 2023). "Suppression of leukemia cell proliferation is indeed consistent with previously reported tumor suppressor function of KLF2, although the mechanism is still unknown." (PMID 37016335, 2023). "Since cholesterol biosynthesis genes were regulated by lovastatin in leukemia cells, we examined whether this regulation is mediated through KLF2." (PMID 37016335, 2023). "KLF2 activation by lovastatin also activated a subset of cholesterol biosynthesis genes that may further contribute to leukemia suppression." (PMID 37016335, 2023). "While the receptor for anti-leukemic activity is still unknown, UM171 shown to activate the growth suppressor genes P21CIP1 and KLF2, which may partially be responsible for leukemia inhibition of this compound." (PMID 36335089, 2022). "We propose that UM171 exerts its effect through two independent pathways (i) HSC expansion markers via PIM1, which could increase leukemia stemness; (ii) growth suppression via as yet to be defined target that controls the tumor suppressor genes KLF2 and P21CIP1." (PMID 36335089, 2022). "We evaluated the correlation between the percentage of leukemia blasts in bone marrow smears of newly diagnosed B-ALL patients and KLF2 expression." (PMID 39906661, 2024). "These splicing perturbations alter the composition of numerous hematopoietic stem and progenitor (KLF2, GATA2, GATA1, SPINK2) or leukemia (LAT2 and NUCB2) regulatory factors." (PMID 36697445, 2023).
leukemia (continued). "Lovastatin inhibits leukemia cell survival and proliferation in part through suppression of the FAM83A/DDIT4/ERK1/2 pathway, mediated by the induction of the tumor suppressor gene KLF2, as well as cholesterol biosynthesis genes." (PMID 37016335, 2023). "As in leukemia, we have shown KLF2 induction independent of the PIM kinase pathway." (PMID 38874684, 2024). "KLF2 induction is not blocked by UM171 and its upregulation is shown to play a role in leukemia inhibition." (PMID 36335089, 2022).
myocardial infarction (6 papers, 2017 to 2022). Gross necrosis of the myocardium, as a result of interruption of the blood supply to the area, as in coronary thrombosis. "It has been reported that HBO treatment induces lncRNA-MALAT1 to target miR-92a/KLF2 for angiogenesis after myocardial infarction." (PMID 35178162, 2022). "HBO induces the enrichment of exo-MALAT1 derived from cardiomyocytes, regulates the expression of CD31 and KLF2 through the MIR92A/KLF2 axis, and promotes cardiac angiogenesis after myocardial infarction." (PMID 34307511, 2021). "HBO‐induced exosomes from cardiac myocytes up‐regulate MALAT1 to suppress miR‐92a expression and counteract the inhibitory effect of miR‐92a on KLF2 and CD31 expression in left ventricular myocardium after myocardial infarction to enhance neovascularization." (PMID 32939962, 2020). "Another study demonstrated that miR-92a increased in the process of endothelial injury after acute myocardial infarction (AMI) and inhibited Kruppel-like factor 2 (KLF2) and KLF4 expression." (PMID 32266263, 2020). "This reduction in KLF2 may be mediated by the reduction of blood flow to the CB during low output heart failure (myocardial infarction-CHF [MI-CHF])." (PMID 28808320, 2017).
diabetic nephropathy (5 papers, 2021 to 2024). "We concluded that Azilsartan alleviated diabetic nephropathy-induced increase in Uterine artery embolization (UAE) mediated by the KLF2/occludin axis." (PMID 38462692, 2024). "In turn, reduced expression of KLF2 potentiates podocyte injury in diabetic nephropathy and increases renal proteinuria." (PMID 37795100, 2023). "Previous studies have shown that decreased endothelial KLF2 expression is related to the development of diabetic nephropathy and Alzheimer’s disease, with respect to vascular inflammation." (PMID 35269384, 2022). "The expression of KLF2 is reduced in diabetic kidneys and it lack aggravates endothelial and podocyte injury in diabetic nephropathy." (PMID 34485320, 2021).
ischemic stroke (5 papers, 2020 to 2025). A stroke disorder caused by obstruction of blood flow to the brain, due to thrombotic (local blood clot formation) or embolic (due to a blood clot or other material traveling from another site) event. "We foresee a more comprehensive and robust understanding of the pleiotropic effects of statins in neuroprotection, as research on statins and KLF2 in ischemic stroke continues to expand." (PMID 39707228, 2024). "In ischemic stroke, KLF2 has recently emerged as a novel therapeutic target, particularly significant in the regulation of BBB function." (PMID 39707228, 2024). "Recent works have revealed that KLF2 overexpression protects against ischemic stroke and alleviates BBB dysfunction by regulating the expression of OCC (occludin, a member of TJ proteins) in endothelial cells." (PMID 36632224, 2023). "It was reported that another KLF family member, KLF2, protected against ischemic stroke-induced BBB disruption and inhibited subsequent brain inflammation." (PMID 36403074, 2022). "Considering that circFndc3b acts as a scaffold for ENO1 to stabilize Klf2 mRNA, these results suggest that exercise may confer neuroprotection after ischemic stroke via the circFndc3b/ENO1/Klf2 pathway." (PMID 39467260, 2025). "Consequently, exercise‐mediated circFndc3b exerted neuroprotective effects in ischemic stroke by regulating the circFndc3b/ENO1/Klf2 pathway and establishing a positive feedback loop via circFndc3b/ENO1/FUS, making circFndc3b a potential therapeutic target for stroke intervention." (PMID 39467260, 2025).
portal hypertension (5 papers, 2017 to 2024). Increased blood pressure in the portal venous system. "Clinical studies appeared that statins, which mainly act on Rho GTPases and Kruppel-like transcription factor 2 (KLF2) signaling, increased the survival of cirrhotic patients with portal hypertension, especially those with concomitant cardiovascular diseases." (PMID 30721324, 2019). "LSECs in cirrhotic livers with evident portal hypertension overexpress Kruppel-like factor 2 (KLF2) to cope with the abnormal hemodynamics of the liver." (PMID 28293634, 2017). "Simvastatin has been shown to reduce portal hypertension through the putative reduction in IHVR by means of several mechanisms, including the induction of KLF2 expression, related to the stimulation of a vasoprotective phenotype in LSECs." (PMID 37896223, 2023).
Sepsis (5 papers, 2016 to 2025). Sepsis is defined as life-threatening organ dysfunction caused by a dysregulated host response to infection. "The KLF2 deficient mice have more severe Gram-positive endotoxin-mediated sepsis and clinical symptoms." (PMID 29125549, 2017). "In vitro KLF2 deficiency induces LPS-mediated sepsis symptoms." (PMID 29125549, 2017). "It was reported that HDAC4, 5, and 7 inhibited KLF2 expression, which in turn had an important role in anti-inflammation, sepsis, and angiogenesis." (PMID 36362263, 2022). "Decreased KLF2 expression has been noted in immune cells in a multitude of inflammatory diseases in humans such as sepsis and coronary artery disease." (PMID 33208733, 2020). "Thus, in addition to the known effects on inhibition of proinflammatory gene expression in myeloid cells, KLF2 in association with HIF-1α could efficiently inhibit the Gram-positive endotoxin-induced effects in sepsis and can efficiently reduce clinical symptoms." (PMID 29125549, 2017). "Additionally, mice with Klf2 deletion in myeloid cells had reduced viability when exposed to high doses of LPS, to mimic conditions of sepsis." (PMID 40534851, 2025). "Role of KLF2 has been shown in sepsis, which is a chronic bacterial infection." (PMID 29125549, 2017). "Together these observations indicate that KLF2 regulates programs that supress inflammatory activation and the absence of KLF2 in macrophages leads to greater antibacterial properties but also increases the unwanted side-effects of unrestrained inflammatory activation, as seen in sepsis." (PMID 40534851, 2025). "It has been shown that KLF2 and hypoxia induced factor-1 alpha (HIF-1α) signaling plays a role in inflammatory regulation induced by Gram-positive endotoxin-mediated sepsis." (PMID 29125549, 2017). "Mφs devoid of KLF2 exhibit enhanced bactericidal activity, and a greater proportion of mice lacking this transcription factor in myeloid cells survive sepsis." (PMID 27302755, 2016).
Stroke (5 papers, 2021 to 2025). Sudden impairment of blood flow to a part of the brain due to occlusion or rupture of an artery to the brain. "Altering the balance between proinflammatory NF-B/p65 and anti-inflammatory KLF-2, results in a proinflammatory phenotype and raises the risk of stroke in sickle cell anemia-diagnosed children." (PMID 36836777, 2023). "Blood outgrowth endothelial cells generated from strokes in children with sickle cell anemia have been found to have reduced levels of KLF-2." (PMID 36836777, 2023). "Overexpression of KLF2 in mice led to smaller stroke volumes and protected against TNF-α-mediated BBB dysfunction." (PMID 36942087, 2023). "Notably, KLF2 has been shown to exert a neuroprotective effect following stroke by regulating the BBB in the cerebral cortex." (PMID 36942087, 2023). "In accordance with our infarct core-to-border axis (punch positions 5–8) analysis, we found that seven of the KLF family of TFs (KLF2–4, 6–8, and 12) were significantly depleted in glutamatergic neurons at the glial scar in the stroke hemisphere (KLF4 and KLF7 shown)." (PMID 33627658, 2021). "KLF2 regulates several key BBB tight junction factors, most notably occludin, thereby serving as a positive mediator of BBB function, reducing compound in the blood into the cerebral vessels and reducing the risk of stroke." (PMID 34867169, 2021). "KLF2, KLF11, MZF1, and MCPIP1 play a protective role in stroke by protecting BBB." (PMID 34867169, 2021).
tuberculosis (5 papers, 2021 to 2025). A chronic, recurrent infection caused by the bacterium Mycobacterium tuberculosis. "Here, a three-gene set (GBP5, DUSP3, and KLF2) in the host whole blood that is robustly diagnostic for active tuberculosis was studied using multiple independent cohorts comprised of children and adults." (PMID 36010011, 2022). "Expression of the 3-gene signature, [guanylate-binding protein (GBP5), dual specificity phosphatase 3 (DUSP3) and Krupple-like factor 2 (KLF2)] was quantified and a tuberculosis (TB) score was calculated using (GBP5+DUSP3)/2-KLF2." (PMID 41430759, 2025). "A novel 3-gene host transcriptional signature (GBP5, DUSP3 and KLF2) has been validated for tuberculosis (TB) treatment monitoring using laboratory-based RNA sequencing platforms." (PMID 34193258, 2021).
Autoimmunity (4 papers, 2021 to 2026). The occurrence of an immune reaction against the organism's own cells or tissues. "Although the KLF2 deficient family members in our study suffered from lymphopenia, autoimmunity or malignancy, additional study cohorts are required to confirm our observations." (PMID 36466816, 2022). "The patients displayed disturbed Treg development, associated with autoimmunity and KLF2 deficiency in experimental models." (PMID 36466816, 2022). "However, we believe that role of KLF2 gene should be considered whenever unexplained familial lymphopenia in association with autoimmunity and an increased risk of malignancy is encountered." (PMID 36466816, 2022). "Our findings highlight KLF2 as a critical regulator of TEC homeostasis and the prevention of autoimmunity." (PMID 41884002, 2026).
cardiac hypertrophy (4 papers, 2021 to 2022). "The AngII-mediated direct and rapid signaling in neutrophils further suggests a potential pathogenic role of myeloid KLF2 in cardiac hypertrophy and failure." (PMID 34793333, 2022). "Nonetheless, neutrophil activation leads to long-term effects on cardiac hypertrophy in our mouse model, likely through a KLF2/NETosis pathway that is also associated with HF in patients." (PMID 34793333, 2022). "This further suggests that hyperactivation of HIF1α signaling resulting from neutrophil KLF2 deficiency exacerbates inflammation and worsens cardiac hypertrophy." (PMID 34793333, 2022). "Myeloid KLF2 deficiency enhances AngII-induced cardiac hypertrophy." (PMID 34793333, 2022). "KLF2-deficient neutrophils are critical for AngII-induced cardiac hypertrophy." (PMID 34793333, 2022). "Altogether, these in vivo studies suggest that, at least in the context of angiotensin II–induced cardiac hypertrophy and failure, loss of KLF2 in neutrophils leads to exacerbated cardiac neutrophil accumulation that in turn promotes cardiac hypertrophy and dysfunction." (PMID 35104806, 2022). "Using the myeloid KLF2–deficient (K2KO) mice as a proinflammatory genetic model, we demonstrated that the neutrophil/KLF2/NET axis is critical for regulating cardiac hypertrophy." (PMID 34793333, 2022). "Collectively, these data demonstrated that myeloid KLF2 is critical in protecting against AngII-induced cardiac hypertrophy." (PMID 34793333, 2022). "Further, we use chronic angiotensin II (AngII) infusion as a classic nonischemic cardiac disease model to show a critical role of neutrophil KLF2 in regulating the development and progression of AngII-induced cardiac hypertrophy." (PMID 34793333, 2022). "recently showed that Kruppel-like factor 2 (KLF2)-deficient neutrophils exhibit enhanced NET formation in vitro and are essential for angiotensin II-induced cardiac hypertrophy." (PMID 36211432, 2022). "Altogether, these in vivo studies support the idea that NETs contribute to the development of cardiac hypertrophy induced by angiotensin II, and that KLF2 opposes NET formation." (PMID 35104806, 2022). "Our data demonstrate that AngII activates neutrophils to mediate cardiac hypertrophy through a KLF2/NETosis/thrombosis pathway." (PMID 34793333, 2022). "Collectively, these transcriptomic and genetic studies indicated that the KLF2/HIF1α axis is critical for AngII-induced neutrophil activation and cardiac hypertrophy, likely through the regulation of NETosis and resultant thrombosis in small vessels of the myocardium." (PMID 34793333, 2022). "Although we found that KLF2 deficiency in macrophages was not the critical determinant of AngII-induced cardiac hypertrophy in this study, one should not exclude the functions of macrophages in HF." (PMID 34793333, 2022). "Collectively, these data demonstrate a critical role of KLF2-deficient neutrophils, rather than macrophages, in the regulation of AngII-induced cardiac hypertrophy." (PMID 34793333, 2022). "KLF2 is critical for the transcriptional regulation of neutrophils in cardiac hypertrophy." (PMID 34793333, 2022). "In this study, we found that simvastatin induced Klf2 expression in endothelium which repressed TGFβ to reduce the size of cardiomyocytes and reactivate the fetal genes, finally contribute to the amelioration of LV hypertrophy in the TAC model." (PMID 33408770, 2021). "In sharp contrast to the Lyz2-K2KO mice with KLF2 deficiency in both macrophages and neutrophils, the Cx3cr1-Cre–driven KLF2-KO mice (designated Cx3cr1-K2KO) did not manifest severe cardiac hypertrophy in response to 4-week AngII infusion." (PMID 34793333, 2022). "Finally, deletion of KLF2 only in monocytes/macrophages did not increase angiotensin II–induced cardiac hypertrophy and dysfunction." (PMID 35104806, 2022).
cardiac hypertrophy (continued). "Furthermore, cardiac function was preserved in both Cx3cr1-Cre and Cx3cr1-K2KO groups, while the cardiac hypertrophy was even less in the Cx3cr1-K2KO group, suggesting the KLF2-deficient macrophages are not the primary driver of AngII-induced cardiac dysfunction." (PMID 34793333, 2022). "On the other hand, mice lacking expression of KLF2 in neutrophils and macrophages exhibited increased neutrophil accumulation, NET formation, and cardiac hypertrophy." (PMID 35104806, 2022).
glioblastoma (4 papers, 2017 to 2024). The most malignant astrocytic tumor (WHO grade IV). "MiR-182-5p in glioblastoma-derived EVs directly targeted Kruppel like factor 2 (KLF2) and KLF4, which resulted in VEGFR accumulation in ECs and thus promoted angiogenesis." (PMID 34966744, 2021). "Studies have proved that XIST impaired formation of neurospheres of glioblastoma via interaction with miR-152 and KLF2." (PMID 29100288, 2017).